OR2A42 (olfactory receptor family 2 subfamily A member 42)
Description:
Odorant receptor.
Tractability: Antibody: its Gene Ontology location is reachable by antibodies, with high confidence; UniProt places it where antibodies can reach, with medium confidence; UniProt predicts a signal peptide or a membrane-spanning region.
Gene: Protein-coding gene on chromosome 7 (144,228,244 to 144,239,605, reverse strand). Ensembl gene ENSG00000212807.
Subcellular location: Cell membrane
Pathways (Reactome):
Sensory Perception: Expression and translocation of olfactory receptors; Olfactory Signaling Pathway
Gene Ontology:
Molecular function: olfactory receptor activity; G protein-coupled receptor activity
Biological process: detection of chemical stimulus involved in sensory perception of smell; G protein-coupled receptor signaling pathway
Cellular component: plasma membrane; membrane
Homologues: Orthologues: macaque OR2A1 (91% identical), dog OR2A9 (84% identical), dog OR2A9B (83% identical), mouse Or2a20 (80% identical), rat Or2a20 (79% identical), mouse Or2a57 (78% identical), rat Or2a57 (78% identical), mouse Or2a51 (78% identical), rat Or2a51 (76% identical). Paralogues in human: OR2A1 (100% identical), OR2A5 (80% identical), OR2A25 (73% identical), OR2A14 (73% identical), OR2A7 (71% identical), OR2A4 (70% identical), OR2A12 (69% identical), OR2A2 (66% identical), OR7C2 (46% identical), OR7C1 (45% identical), OR1C1 (45% identical), OR7A10 (45% identical), and 116 more.